APOE (apolipoprotein E)
Diseases named in the same sentence as APOE in open-access papers (continued):
Sharing a sentence is not in itself a finding about the gene and the disease.
atherosclerosis (continued). "Also, gluten diet can exacerbate vascular oxidative stress and inflammation and accelerate atherosclerosis in ApoE knockout mice." (PMID 33062134, 2020). "Additionally, in the apolipoprotein E (apo-E)-deficient mouse model with streptozotocin-induced hyperglycemia, DMF reduced the development of atherosclerosis." (PMID 33348578, 2020). "There was evidence of an interaction between atherosclerosis and APOE ε4 status on AD30." (PMID 31919381, 2020). "Additionally, apoE-/- mice treated with morin hydrate exhibit attenuated atherosclerosis development, decreased serum levels of pro-inflammatory factors (TNF-α, ICAM-1) and enhanced autophagy in plaques." (PMID 33154191, 2020). "Therefore, we suggest that the observed upregulation in ApoE−/− mice reflects the effect of developing atherosclerosis." (PMID 33255872, 2020). "Interestingly, in the apolipoprotein-E (ApoE-/-) mice, the animal models for high fat-diet induced atherosclerosis in human arteries, the presence of TCs has been correlated to angiogenesis, repair and homeostasis in the heart, liver and kidney." (PMID 32192184, 2020). "The differential response to individual peptide stimulation between female and male mice also suggested that there were inherent differences in the immune profile between female and male apoE–/– mice that may influence atherosclerosis." (PMID 32373127, 2020). "APOE*3Leiden.CETP mice, a translational model for hyperlipidaemia and atherosclerosis, were used to evaluate the mechanisms underlying the lipid‐lowering effect of icosabutate and its effect on atherosclerosis." (PMID 32841505, 2020). "To test the hypothesis that long-term administration with TFA would protect against atherosclerosis, we treated atherogenic apoE−/− mice with TFA and HFD for 16 weeks." (PMID 33381046, 2020). "Notably, dietary supplementation with resveratrol (a stilbenoid polyphenol) increased the abundance of Lactobacillus, reduced the levels of TMAO and attenuated the atherosclerosis phenotype of ApoE-/- mice fed a high-choline diet." (PMID 32764281, 2020). "The development of ApoE−/− zebrafish would create a new tool for atherosclerosis research that could be compared with mouse models." (PMID 32714944, 2020). "We test whether the hydrophobic fungal siderophore DFC, produced by Neurospora crassa, owns beneficial effects in a widely used animal model for atherosclerosis that is ApoE−/− mice." (PMID 32635347, 2020). "ApoE−/− mice were excellent model for experimental atherosclerosis research." (PMID 33276745, 2020). "Although it was shown that atherosclerosis in the ApoE-/- mice was prevented by fucoidan in a few reports, the molecule mechanism of the protection remains unknown." (PMID 33505579, 2020). "Moreover, ubiquitous or VSMC-specific progerin expression accelerates atherosclerosis in atherosclerosis-prone Apolipoprotein e-null mice (Apoe−/−), at least in part due to excessive endoplasmic reticulum stress and associated unfolded protein response." (PMID 32182706, 2020). "Other studies indicate that lack of IL-1β decreases the severity of atherosclerosis in ApoE-deficient mice, and antibodies targeting mouse IL-1 have resulted in reduced atherogenesis; whereas, exogenous IL-1β increases intimal medial thickening." (PMID 33025148, 2020). "A recent study reported that deficiency of IL-23 significantly decreased IL-22 expression in ApoE-knockout mice, and also reduced expression of IL-22, thereby relieving the release of inflammatory substances, and thus alleviating the process of atherosclerosis." (PMID 32194399, 2020). "To examine whether coal-fired PM2.5 promotes the formation of atherosclerosis in ApoE−/− mice, we exposed them to coal-fired PM2.5 or PBS for 8 weeks." (PMID 32384920, 2020).
atherosclerosis (continued). "Furthermore, the role of T cells reactive to LL-37 in atherosclerosis was assessed using apoE−/− mice immunized with the LL-37 mouse ortholog, mCRAMP." (PMID 33123157, 2020). "The beneficial of HFD-induced atherosclerotic mouse model than spontaneously developing atherosclerotic lesions by SCD-fed ApoE−/− mouse model is that HFD can accelerate the progression of atherosclerosis and also elevate AST and ALT levels to increase the risk of developing CVD." (PMID 32472055, 2020). "Finally, another polyphenol contained in apple such as chlorogenic acid potently reduces atherosclerosis development in ApoE-/- mice due to its hypolipidemic, anti-inflammatory, and antioxidant properties." (PMID 33198144, 2020). "Moreover, epicatechin was shown to attenuate pro-atherogenic inflammatory processes in female ApoE*3-Leiden transgenic mice, a well-established model of hyperlipidemia and atherosclerosis induced by diet." (PMID 33322700, 2020). "The ApoE KO rats are a new model to study endothelial dysfunction during the earlier stages of atherosclerosis and could help us improve preclinical drug development." (PMID 32943715, 2020). "ApoE−/− mice are a widely used murine model for atherosclerosis." (PMID 32566106, 2020). "We examined the effects of bvPLA2 on atherosclerosis using ApoE-/- and ApoE-/-/Foxp3DTR mice." (PMID 32977607, 2020). "This peptide is a 10-residue peptide spanning the predicted class G* amphipathic helix 6 from apoJ and has been successfully used to retard atherosclerosis in apoE-knockout mice, which was attributed to its capacity to improve the anti-inflammatory properties of HDL." (PMID 32485898, 2020). "Moreover, resveratrol derived from Polygonum cuspidatum was demonstrated to attenuate TMAO-induced atherosclerosis in apoE-/- mice by remodelling microbiota as well as decreasing TMAO and BA levels." (PMID 33062141, 2020). "The expression of MMP-9, which serves as an established marker for inflammation during atherosclerosis progression, shows a strong upregulation in ApoE−/− mice due to high-fat diet induced plaque development after 22 weeks, while control animals only show a low upregulation." (PMID 33255872, 2020). "In order to address whether miR-145 treatment can attenuate the development of vascular lesions, we performed early intervention studies in ApoE−/− mice, a model of atherosclerosis on a western diet." (PMID 30941422, 2020). "This was however out of the scope of our study into whether Western diet can accelerate endothelial dysfunction and earlier atherosclerosis in ApoE KO rats specifically." (PMID 32943715, 2020). "Such HDL disturbances could be related to accelerated atherosclerosis development and higher risk of incident CVD, since it has been proven that the lower amount of HDL as well as lower APOE content in HDL impair all steps of RCT." (PMID 30851738, 2019). "Next, we hypothesized that deletion of the miR-106b~ 25 cluster in ApoE KO mice would have a functional effect on the progression of atherosclerosis." (PMID 31796057, 2019). "STZ-induced ApoE-/- mice were commonly used to establish diabetic atherosclerosis models." (PMID 31080547, 2019). "Studies have shown that ApoE−/− mice can develop atherosclerosis at 12 weeks on a high-fat diet." (PMID 31521120, 2019). "Prolonged secretion of these myokines for 20 weeks may be involved in suppression of atherosclerosis in exercise-trained ApoE-KO mice." (PMID 30858489, 2019). "HNG-F6A reduces oxidative stress and prevents atherosclerosis progression in ApoE knockout mice." (PMID 31214116, 2019). "Without IL-1, vascular inflammation and atherosclerosis do not develop in apolipoprotein E-deficient mice, and arthritis does not develop with collagen induction." (PMID 31394758, 2019). "In this study, we investigated whether skeletal muscle-specific PGC-1α overexpression suppresses atherosclerosis using a murine ApoE-KO model." (PMID 30858489, 2019).
atherosclerosis (continued). "A previous study found that recombinant human IL-35 reduced the serum levels of TC and TG, but not affected the LDL-C and HDL-C levels in ApoE-/- mice, indicating that the effect of IL-35 on lowering lipids is associated with the reduction of atherosclerosis." (PMID 31093011, 2019). "Firstly, IL-1α played an important role in atherosclerosis development in the ApoE−/− mice model." (PMID 31354731, 2019). "Increased plasma ApoE may contribute to altered VLDL metabolism and to increased atherosclerosis susceptibility in NAFLD." (PMID 31386691, 2019). "Moreover, mTOR enhances foam cell formation and, inhibiting mTOR, enhances ox-LDL-induced autophagy in vitro and restricts atherosclerosis in ApoE−/− mice." (PMID 31214032, 2019). "Because both NLRP3 and caspase-1 deficiency decreases atherosclerosis in ApoE-/- mice, therapeutic modulation of NLRP3 or caspase-1 activity is likely to offer significant health benefits for patients with severe atherosclerosis." (PMID 31019462, 2019). "Chronic OSM administration in APOE*3Leiden.CETP mice reduced atherosclerosis development." (PMID 31461490, 2019). "It has been reported that 3 weeks of exercise training could increase plasma myokines concentrations (2.5-fold for Irisin20 and 1.2-fold for BAIBA21), and exercise training for 20 weeks suppressed atherosclerosis in ApoE-KO mice." (PMID 30858489, 2019). "Consistently, Khallou-Laschet and his colleagues found that regardless of the atherosclerosis stage, the prevalence of the M2 phenotype was associated with smaller plaque surface areas in ApoE KO mice." (PMID 30923552, 2019). "Overexpression of Irisin alleviated atherosclerosis in ApoE-/- mice." (PMID 31191305, 2019). "In a study on apolipoprotein E-deficient (Apoe−/−) mice, intraperitoneal injection of SAP was shown to inhibit atherosclerosis in these animals, expression of SAP increased in hemorrhagic atherosclerotic plaques of carotid arteries, compared with fibrous plaques." (PMID 31703357, 2019). "Furthermore, AMP-dNM treatment was shown to reduce the development of atherosclerosis in APOE*3-Leiden and low-density lipoprotein receptor -/- mice by lowering plasma cholesterol levels." (PMID 31013778, 2019). "In this study, we surveyed the role of chemerin in progression of atherosclerosis in ApoE−/− mice." (PMID 31781638, 2019). "Atherosclerosis was studied in aorta of ApoE−/− mice fed western-style diet." (PMID 30692584, 2019). "In the present study we attempt to further characterize the splenic IL25-induced ILC2 subset (Lin−CD45+IL17RB+ICOS+IL7raintermediate) as well as investigate the cells subset’s direct effect on atherosclerosis development through its adoptive transfer to atherosclerosis-prone apoE−/− mice." (PMID 31823769, 2019). "Nicotine was administered to ApoE-/- mice with atherosclerosis to determine whether nicotine stimulation increases susceptibility to atherosclerosis." (PMID 31660076, 2019). "Moreover, it has been demonstrated that apoE plays an important role in atherosclerosis by modifying inflammatory responses and facilitating cholesterol efflux from cells." (PMID 30996342, 2019). "In addition, LbCpf1 had been already in use to generate an APOE knockout rat which can be used as an initial-to-early atherosclerosis model." (PMID 31086658, 2019).
atherosclerosis (continued). "In apoE-deficient mice, MEF2A inhibition accelerates atherosclerosis." (PMID 31182679, 2019). "Moreover, the up-regulation of immune response and immune globulin production by altered expression of mRNAs and lncRNAs in ApoE−/− mice reflects the important role of the immune response in the process of atherosclerosis." (PMID 31446617, 2019). "Specifically, in the setting of atherosclerosis, it was demonstrated that gut-colonization of germ-free ApoE mice with strains of bacteria which differed in butyrate production; could affect the progression of atherosclerosis." (PMID 31849973, 2019). "These opposite regulatory mechanisms of apoE in the liver and macrophages under inflammatory conditions may synergize to promote the evolution of atherosclerosis." (PMID 30909560, 2019). "To study the role of the B2 bradykinin receptor (Bdkrb2) in atherosclerosis, we used (i) ApoE–/– mice with endogenously expressed Bdkrb2, (ii) ApoE–/– mice with Bdkrb2 deficiency, and (iii) ApoE–/– mice with moderately increased transgenic BDKRB2 expression level." (PMID 30847343, 2019). "Atherosclerosis was induced in ApoE–/– mice and those with ApoE–/– and TP–/–." (PMID 31611817, 2019). "According to one study of macrophage phenotypes during the progression of atherosclerosis in ApoE–/– mice, serial immunohistological examinations showed that plaque macrophages have M2 phenotypes at the early stages of the disease but become M1 macrophages as the lesions advance." (PMID 30923552, 2019). "The recent studies published by Tan and Sharma’s group demonstrated that the bardoxolone analog, dh404, at low doses, attenuates atherosclerosis in diabetic Apolipoprotein E (ApoE) knockout mice and protects against diabetes-induced endothelial dysfunction, both in vivo and in vitro." (PMID 31031630, 2019). "Moreover, one study suggests that 10,12 CLA actually worsens aortic sinus atherosclerosis levels in apoE−/− mice." (PMID 30754681, 2019). "The NCEH1 isoform accelerates atherosclerosis in ApoE−/− mice." (PMID 31653058, 2019). "In vivo, overexpression of Irisin alleviated atherosclerosis in ApoE-/- mice." (PMID 31191305, 2019). "The author concluded that HHcy suppresses the function of Tregs, which may be responsible for HHcy-accelerated atherosclerosis in apoE-/- mice." (PMID 31670376, 2019). "Based on previous work supporting favorable cardiometabolic effects of GCE and CGA administration, we first investigated whether our standardized GCE affected atherosclerosis development in dyslipidemic ApoE-/- mice." (PMID 30818779, 2019). "The aim of this study was to investigate whether the nuclear receptor farnesoid X receptor (FXR) could regulate FNDC5/Irisin expression and the role of Irisin in hyperlipidemia and atherosclerosis in ApoE-/- mice." (PMID 31191305, 2019). "Using B cell-deficient atherogenic ApoE−/− mouse model, we examined atherosclerosis development in the absence of B cells and examined atherosclerosis development again after transfer of different B cells." (PMID 31998318, 2019). "Further efforts are warranted to assess whether EC‐specific progerin expression is sufficient to aggravate atheroma formation in atherosclerosis‐prone mouse models (e.g., apolipoprotein E‐null mice and low‐density lipoprotein receptor‐null mice)." (PMID 30884114, 2019). "In this study, we found that C8:0, which is a member of the MCFAs, could suppress inflammatory signaling via the TLR4/NF-κB pathway and improve atherosclerosis in apoE−/− mice." (PMID 31182969, 2019). "Additionally, exogenous rIL-35 treatment reversed the imbalance of Th17/Treg and attenuated atherosclerosis in ApoE-/- mice." (PMID 31093011, 2019).
atherosclerosis (continued). "Because BDKRB2 enhanced the endothelial dysfunction of Tg-B2++ApoE–/– mice, we asked whether inhibition of ACE-dependent angiotensin II generation in Tg-B2++ApoE–/– mice could retard the BDKRB2-enhanced atherosclerosis progression." (PMID 30847343, 2019). "In a mouse high-fat diet-induced atherosclerosis model, TRPA1 was localized mainly in macrophages; TRPA1 channel activation with AITC suppressed the progression of atherosclerosis in apolipoprotein E (apoE)−/− mice, while the protective effect was lost in apoE−/−TRPA1−/− mice." (PMID 31680989, 2019). "Exosomes derived from insulin resistance adipocyte in diabetic ApoE deficit mice could promote atherosclerosis and vulnerable plaque via vasa vasorum angiogenesis." (PMID 31595163, 2019). "In summary, hydroxy-α-sanshool (HAS) could play a significant role in improving the lipid profile and may act as a protective agent against atherosclerosis by regulating of PPARγ and APOE to reduce lipid peroxidation." (PMID 31534622, 2019). "Moreover, olanzapine has been found to deregulate hepatic lipid metabolism and exacerbate atherosclerosis in apolipoprotein E-null (apoE-/-) mice." (PMID 31261805, 2019). "Further, ApoE−/− mice are frequently used and are valuable tools in atherosclerosis research." (PMID 31817202, 2019). "To investigate this hypothesis we transferred DNT5 to a mouse model in which atherosclerosis is accelerated by a combination of ApoE gene disruption and western-style diet to elevate plasma cholesterol." (PMID 30692584, 2019). "Notably, the ChemR23 receptor agonist chemerin-p decreases atherosclerosis after 4 weeks treatment in apoE knock-out mice." (PMID 31696250, 2019). "ApoE−/− mice exposed to concentrated ambient particles (CAPs) had accelerated atherosclerosis development and reduced cardiac function, while these responses in mice exposed to CAPs denuded of organic chemicals were not statistically different from mice exposed to air." (PMID 31439044, 2019). "Additionally, the KO/KO mice remain at the initial stage of atherosclerosis, as ApoE KO mice progressively developed into the advanced stage of this process." (PMID 30302668, 2019). "Additionally, an elevation of 27-hydroxycholesterol in cyp7b1 KO/apoE KO mice exacerbated atherosclerosis and subcutaneous injection with 27-hydroxycholesterol to apoE KO mice increased atherosclerosis." (PMID 31382484, 2019). "Accordingly, Cxcr4 expression in the BM cells of aged ApoE−/− mice was also decreased, and BM cell engraftment was impaired which may contribute to the progression of atherosclerosis in ApoE−/− mice." (PMID 31385396, 2019). "Overexpression of Irisin decreased hyperlipidemia and alleviated atherosclerosis in ApoE-/- mice." (PMID 31191305, 2019). "Adoptive transfer of B cells deficient in either MHCII or co-stimulatory molecule CD40, molecules required for B and CD4 T cell interaction, into B cell-deficient μMT−/− ApoE−/− mice failed to increase atherosclerosis." (PMID 31998318, 2019). "Genetic deletion of CSE exaggerates atherosclerosis in ApoE-/- mice, and treatment of CSE-knockout mice with H2S inhibits the development of atherosclerosis, pinpointing that endogenous H2S may be of benefit in the treatment of atherosclerosis." (PMID 32038245, 2019).